RNU6-958P (RNA, U6 small nuclear 958, pseudogene)
Gene: Small nuclear RNA gene on chromosome 2 (43,408,307 to 43,408,412, forward strand). Ensembl gene ENSG00000252804.
Homologues: Orthologues: chimpanzee U6 (98% identical), macaque U6 (95% identical), dog U6 (66% identical), rabbit U6 (63% identical), mouse Gm25792 (61% identical), guinea pig U6 (57% identical), rat LOC120103222 (55% identical). Paralogues in human: RNU6-98P (74% identical), RNU6-429P (72% identical), RNU6-17P (71% identical), RNU6-18P (71% identical), RNU6-338P (71% identical), RNU6-1 (70% identical), RNU6-11P (70% identical), RNU6-12P (70% identical), RNU6-13P (70% identical), RNU6-16P (70% identical), RNU6-2 (70% identical), RNU6-25P (70% identical), and 1288 more.